CXCL12 (C-X-C motif chemokine ligand 12)
Diseases named in the same sentence as CXCL12 in open-access papers (continued):
Sharing a sentence is not in itself a finding about the gene and the disease.
tumor (continued). "CXCR4 and its ligand, CXC chemokine ligand 12 (CXCL12), have been shown to be key regulators of tumor invasion and metastasis." (PMID 36103228, 2022). "CXCR4 is highly expressed in PDA and is also expressed by T cells, leading to their immobilization within tumor sites via CXCR4 binding to the stromal derived factor-1 (SDF-1) or else known as CXCL12." (PMID 35466279, 2022). "Tumor-associated macrophages (TAMs) have been reported to be associated consisting of highly expressed CCL2, CCL3, CCL5, CCL18, CXCL1, and CXCL12 in the TME." (PMID 35935996, 2022). "Pharmacological agents targeting the CXCR4/CXCL12 axis were developed to inhibit tumor growth and metastasis and also mobilize hematopoietic stem cells to the periphery for subsequent transplantation." (PMID 33603130, 2022). "SDF1 binds primarily to CXC chemokine receptor 4 (CXCR4), while the CXCL12/CXCR4 axis has a significant role in tumor progression, metastasis, and cancer cachexia." (PMID 35454797, 2022). "Meanwhile, CXCL12 expression in tumor promoted the recruitment of CXCR4-expressing immune cells to potentiate the tumor-promoting effect." (PMID 35729596, 2022). "Tumor cells can express CXCL12 in a paracrine mode; this stimulates tumor stromal cells to produce tumor necrosis factors, thus promoting the growth of tumor cells." (PMID 35893797, 2022). "Intriguingly, previous reports have shown that overexpression of PDGF-B can increase tumor pericyte content via induction of CXCL12 expression by endothelial cells within the TME38." (PMID 36192379, 2022). "This study showed that CXCL12 contributes to the differentiation of bone marrow stem cells into pericytes and the overall number of pericytes present at the site of the fibrotic tumor." (PMID 35831901, 2022). "Binding of CXCL12 to CXCR4 on tumor cells can inhibit the apoptosis of tumor cells and promote the epithelial-to-mesenchymal transition." (PMID 35169832, 2022). "Here, we show that 7HP349 integrin activation reversed CXCL12’s effects on tumor-specific CD8+ Teffs, promoting CD8+ Teff persistence and functionality, as evidenced by an increase in IFN-γ secretion." (PMID 35552271, 2022). "Our study suggests that miR‐126 affects the function of macrophages, subsequently suppresses epithelial transformation and ultimately inhibits tumour development via CXCL12/IL‐6 signalling." (PMID 35363937, 2022). "In ovarian cancer, BM-MSCs produce CXCL-12 to promote thermotolerance, which can protect tumour cells against chemotherapy." (PMID 35869057, 2022). "CXCL12 concentrations were significantly higher in ESCC tumor homogenates than in plasmas of ESCC patients (P = 0.038)." (PMID 35941662, 2022). "Blockade of CXCR4 is thought to inhibit all the steps necessary for the development of metastatic foci: not only tumour cell infiltration into CXCL12-producing predestination organs, but also adhesion, migration, invasion and tumour angiogenesis." (PMID 36140541, 2022). "Primary tumors must engage blood vessels to promote tumor cell dissemination (angiogenesis), which contains interactions of tumor-cell-endothelial cell and the recruitment of blood vessels by growth factors, namely, CXCL12, FGF, and VEGF-A." (PMID 35514980, 2022). "Gao demonstrated that triptolide has the ability to reshape the immune microenvironment of colon cancer, and its main mechanism is to reduce tumor-associated macrophage infiltration and M2 polarization by inhibiting tumor-derived CXCL12." (PMID 35443712, 2022). "Pharmacological studies targeting CXCR4/CXCL12 axis demonstrated that CXCR4 antagonist releases T cells from CXCL12-rich stroma and increases T cell infiltration to tumor sites." (PMID 35265130, 2022). "The so-called inflammatory CAFs (iCAFs) that express ALDH1A1, KLF4, LEPR, and CXCL12 were distributed across the areas that contain both tumor and immune-stromal cells, whereas the myofibroblast CAFs were enriched only in the tumor cell-enriched area." (PMID 36376874, 2022).
tumor (continued). "CXCR4 is a transmembrane G-protein coupled-receptor activated by CXCL12, which is involved in tumor growth, invasion, angiogenesis, and TAM recruitment via the activation of signaling pathways such as MEK/ERK and PI3K/mTOR." (PMID 36311702, 2022). "Next, we ascertained that metformin prevents a motile phenotype of BCAHC-1 cells triggered by the paracrine liaison between tumor cells and CAFs upon insulin activated CXCL12/CXCR4 axis." (PMID 35672854, 2022). "In general, cytokines and chemokines are mediators of PCa progression and CXCL12 gradients are essential for tumor cell transmigration and metastasis." (PMID 35717322, 2022). "CXCL12 is known to be produced mainly by fibroblast activation protein (FAP)-expressing CAFs in the tumor microenvironment." (PMID 35884382, 2022). "It was shown that a decrease in the expression level of CXCL12 in MSCs contributed to the metastasis of tumor cells." (PMID 36354566, 2022). "There is evidence that CXCR4 is expressed in ovarian cancer primary tumours and its ligand CXCL12 is expressed in the ascitic fluid." (PMID 36140541, 2022). "Subsequent CXCL12 inhibition slowed tumour growth and increased tumour infiltration by cytotoxic T-cells." (PMID 36358721, 2022). "The gradient established between CXCR‐4 expressed on tumour cells and CXCL12 produced by stromal and lymphatic endothelial cells enhances tumour cell metastasis." (PMID 36398426, 2022). "In vivo, CXCL12 accelerates tumor growth through induction of angiogenesis, cell proliferation and inhibition of apoptosis." (PMID 35406582, 2022). "It is a newly discovered chemokine receptor for C-X-C motif chemokine ligand 12 (CXCL12) and is highly expressed in multiple cancers and plays a crucial role in tumor growth and metastasis." (PMID 35443745, 2022). "In vivo, valproate treatment of APC mutant mice (APCMin/+) decreases the number of intestinal tumors and slows down tumor growth in ectopic xenografts while restoring CXCL12 expression." (PMID 35406582, 2022). "Functionally and mechanistically, miR-200b-3p is a tumor suppressor in GC by targeting CXCL12/CXCR7 pathway." (PMID 35226830, 2022). "CXCL12 is a pivotal regulator of the tumor microenvironment regulating multiple oncogenic processes such as angiogenesis, osteoclastogenesis, or tumor cell migration and adhesion to stromal cells." (PMID 35064098, 2022). "More specifically, mesenchymal stromal cells (MSCs) can be recruited to the stroma of developing tumors to enhance metastasis through their ability to secrete growth factors such as CXCL12 to promote tumor cell proliferation and tumor angiogenesis." (PMID 35406582, 2022). "Circulating EPCs follow a CXCL12 gradient towards the tumor bed and then integrate into the nascent vessels." (PMID 35203510, 2022). "CAFs have been shown to secrete immunosuppressive ligands such as TGF-β and CXCL12, which can prevent cytotoxic T-cell activity and migration into the tumor and recruit immunosuppressive populations such as MDSCs and neutrophils." (PMID 36010986, 2022). "The CXCL12/CXCR4 biological axis is also closely related to tumor angiogenesis, and blocking this axis can inhibit tumor angiogenesis either by inhibiting VEGF or directly." (PMID 35770088, 2022). "Intriguingly, we were unable to correlate the distinct mode of interaction on tumor cell migration with the previously established use of distinct CXCL12 and CXCL11 receptors in the migratory response of the respective tumor cells." (PMID 36539774, 2022). "Different downstream pathways, such as the mitogen-activated protein kinases (MAPK) cascades, convey CXCL12 signal via CXCR4/ACKR3 with roles in tumor biology." (PMID 36233192, 2022). "The increase in CXCL12 and CXCR4 expression observed by us confirms the important role of the CXCL12/CXCR4 pathway in tumor development and metastasis." (PMID 36012171, 2022).
tumor (continued). "Combining anti-CXCL12 monotherapy with pembrolizumab triggered activation and clustering of T cells in the tumor core and led to long-term disease stabilization in patients with pretreated advanced metastatic colorectal cancer." (PMID 35615089, 2022). "For instance, CXCL12 regulates interactions between tumor cells and surrounding cells in the tumor microenvironment, promoting tumor survival, proliferation, angiogenesis, and metastasis." (PMID 36010899, 2022). "This has been associated with several mechanisms involving mediator-produced CAFs including expression of CXCL12 that mediates T cell exclusion from the tumor and resistance to immunotherapy via CXCR4." (PMID 35977489, 2022). "The autocrine CXCR4/CXCL12 pathway is known to activate MSCs into tumor-promoting CAFs29,43 and subsequently increases survival, migration, and cytokine secretion through PI3K/AKT signaling." (PMID 34971821, 2022). "The CXCL12/CXCR4 axis can induce the proliferation of tumor cells via activation of the ERK and AKT signaling pathways." (PMID 35893797, 2022). "CXCL12 activates tumor cells and attracts Tregs and MDSCs by binding with its receptor CXCR4 to induce angiogenesis and create an immunosuppressive environment for tumor cell proliferation." (PMID 35083488, 2022). "In the next section, we focus on the role of the CXCL12/CXCR4 axis in the tumor microenvironment (TME)." (PMID 35893797, 2022). "The deletion of the CXCL12 gene specifically in Pdgfr+ adipose stromal cells suppressed tumor growth and EMT, indicating that adipose stromal cells represent the main source of CXCL12." (PMID 35406450, 2022). "Studies have reported that tumor metastasis target tissues frequently express high levels of CXCL12." (PMID 35729596, 2022). "The striking difference is that CXCL12 acts as a tumor promoter, while BoxA promotes tumor cell phagocytosis and tumor rejection, protecting mice from a rechallenge due to a robust immunological memory." (PMID 36293358, 2022). "In GC, miR-204-5p is discovered to target the 3′-UTR of CXCL12 as a tumor suppressor, regulating invasion and migration." (PMID 35647303, 2022). "CXCR4 can direct the migration of CD8 T cells and NK cells to tumor sites but can also impede the infiltration of T cells to tumor cells through CXCL12." (PMID 35265130, 2022). "ILC3s are known to produce IL-17 and CXCL12, which play a role in tumorigenesis, angiogenesis, and tumor growth." (PMID 36419156, 2022). "Next, we analyzed MDSC chemotaxis-related genes, including Cxcl1, Cxcl2, Cxcl5, and Cxcl12 in tumor tissues." (PMID 34976216, 2022). "CXCR4, CXCL12, and CXCR7 are overexpressed in NETs and are associated with a higher tumor grade and advanced tumor stage." (PMID 36551599, 2022). "And the CXCL12/CXCR4 axis in PDA is a promoter of tumor proliferation, invasion and chemoresistance." (PMID 36131941, 2022). "Fucoidan crude extracts bind CXCL12 and inhibit lung metastasis and tumor growth in 4T1 breast cancer cells." (PMID 35080679, 2022). "The nanobody reduced the viability of tumour cells at a low dose, inhibited CXCL12-induced tumour migration and enhanced the cytotoxicity of hPBMCs in vitro." (PMID 36284271, 2022). "We demonstrate the existence of complex interplay between the CXCL11- and CXCL12-chemokine systems, which differs with respect to tumor cell type and cellular function." (PMID 36539774, 2022). "CXCL12/CXCR4 axis is another molecular target for cancer treatment as this axis leads to an immunosuppressive tumor microenvironment." (PMID 35638450, 2022). "Since chemokines, such as CCL2 and CXCL12, can regulate tumor behavior similar to metastasis, their levels were also determined." (PMID 36012284, 2022). "Similar to TAMs, CAFs have also been shown to stimulate cancer cell growth and tumor angiogenesis by enhancing stromal cell derived factor‐1 (SDF‐1)/CXCL12 signaling in CRC." (PMID 35791509, 2022).
tumor (continued). "Our present demonstration that depending on the tumor cell type, a combination of CXCL12 and CXCL11 either allows for pro- or anti-tumor activity put caution on ongoing efforts to establish chemokine receptors as therapeutic targets in cancer." (PMID 36539774, 2022). "To exclude that analysis is biased by chemokine-induced cell proliferation, we maintained the various tumor cells with CXCL12, CXCL11 or both for 48 h and determined numbers of proliferating cells by BrdU-labeling." (PMID 36539774, 2022). "TGFB1, IL-6 and CXCL12 played an important role in the cell-cell communication between residual tumor cells and CAFs." (PMID 35784460, 2022). "NOX-A12, an inhibitor of chemokines, is conducive to inhibiting CXCL12 and improving sensitivity to anti-PD-1 therapy by attracting T cells and NK cells to the tumor." (PMID 35935996, 2022). "The CXCR4/CXCL12 axis plays a relevant role in shaping the tumor microenvironment (TME), mainly towards dampening immune responses." (PMID 35565443, 2022). "GBM cells disrupt the integrity of the blood-brain barrier (BBB) during tumor initiation and release multiple cytokines such as the chemokine stromal cell-derived factor 1-α (CXCL12) to recruit monocytes or macrophages to the tumor site." (PMID 36311702, 2022). "CXR4 is expressed at the surface of tumor cells and is activated by CXCL12 which is expressed in the stroma or in organs that are preferred sites of metastasis such as lung or bone-marrow." (PMID 35454943, 2022). "The binding of CXCL12 (stromal cell-derived factor 1) to CXCR4 on tumor cells enhances proliferation, either via MAPK or PI3K/Akt pathways, and CXCL12 also recruits immunosuppressive cells as Tregs and MDSC that contribute to immune evasion." (PMID 35504900, 2022). "LARC cells after nCRT demonstrated increased CXCL12 expression in the plasma membrane, suggesting a connection with their capacity for chemoradioresistance and to reinitiate tumor growth and metastasis." (PMID 34976180, 2022). "The findings from our neutrophil depletion study in the LLC1 tumor model provided evidence that neutrophils are a major source of CXCL12 at the TME." (PMID 35552271, 2022). "These demonstrate that the CXCR7/CXCL12 axis promotes tumor growth and metastasis by activating the STAT3 pathway in EC." (PMID 35264069, 2022). "VEGF chemokine induces the expression of the C-X-C motif Chemokine ligand 12 (CXCL12) are chemokines formed by the activation of myofibroblasts and tumor macrophages." (PMID 36518665, 2022). "Studies further exhibited that chemokine/receptor pairs like CXCL12/CXCR4/CXCR7, CXCL16/CXCR6, and CX3CL1/CX3CR1 were obviously associated with tumor progression." (PMID 35419058, 2022). "The effect of NFκB activity in PSCs on promoting tumour growth by increasing expression of CXCL12 in iCAFs has also been demonstrated." (PMID 36358721, 2022). "Several studies have reported that CXCL12 can stimulate the proliferation of various tumor cell lines, including melanoma, glioma, small cell lung cancer, gastric cancer, pancreatic cancer, and CRC." (PMID 35702353, 2022). "The paracrine cytokines secreted by cancer-associated fibroblasts, such as TGFβ, CXCL12, CCL2 and IL-6, have been identified as important signaling molecules for tumor progression and immunosuppression in the microenvironment." (PMID 35628489, 2022). "CXCR4 antagonists can block CXCL12-dependent growth and proliferation signals, inhibit tumor cell metastasis and angiogenesis, and reduce drug resistance in tumor cells." (PMID 35893797, 2022). "CXCR4/CXCL12 signaling also activates the Hh pathway in other cancer types, thus increasing tumor size, cell motility, angiogenesis, EMT, cell invasion, and NANOG expression." (PMID 36118530, 2022). "Implicated CAF-derived factors in tumour development include TGFβ, LIF, CXCL12, IL6, IGF1, and MAPK and STAT3 signalling pathways." (PMID 36358721, 2022).
tumor (continued). "The IL-6/JAK2/STAT3 pathway and CXCL12/CXCR4 interactions between tumor cells and CAFs were enriched." (PMID 35784460, 2022). "Collectively, these findings establish that CXCL12 and CXCL11 additively or synergistically promote invasion of some tumor cells whereas in other tumor cells CXCL11 seems to suppress the stimulatory effects of CXCL12 on cell invasion." (PMID 36539774, 2022). "Mesenchymal stem cells (MSCs) are a heterogeneous group of progenitor cells with tumor tropism properties that are continuously recruited and integrated into the tumor microenvironment (TME) in response to chemokines such as CXCL12." (PMID 35835756, 2022). "The CXCL-12/CXCR4 axis correlates with tumor growth, invasion, angiogenesis and metastasis in CRC, making this chemokine axis to one of the most promising targets for an inhibitory therapy." (PMID 36611932, 2022). "For example, anti-angiogenic drugs such as anti-CXCL12 or Vstat120, can increase tumor hypoxia and necrosis which stimulates the secretion of pro-angiogenic factors and therefore promotes tumor growth." (PMID 35155581, 2022). "The CXCL12/CXCR4 axis mediates the directional migration of CXCR4-positive tumor cells to CXCL12-expressing organs such as LNs and the liver." (PMID 35877436, 2022). "Pancreatic stellate cells can increase CXCL12 expression via the NF-kB pathway, thus promoting tumour growth and preventing cytotoxic T cells from infiltrating the tumour and killing cancer cells." (PMID 35468838, 2022). "CXCL12 promotes tumor spread by mediating malignant cells via the endothelial vessel wall and extracellular matrix." (PMID 35655917, 2022). "During homing, the CXCR4 expressed by HSCs and breast cancer cells binds to the CXC chemokine ligand 12 (CXCL12) expressed by bone marrow stromal cells, such as osteoblasts, endothelial cells, and fibroblasts, to retain HSCs or tumor cells in the bone marrow." (PMID 36497209, 2022). "Some levels of VEGF and CXCL12 are still present in the tumours grown in fibroblast-specific Atf4 KOs and therefore we cannot exclude some additional contribution from other sources." (PMID 35654839, 2022). "The cooperation between Notch and CXCR4/CXCL12 has been reported in tumor angiogenesis and hematological malignancies." (PMID 36266453, 2022). "PGE2 is involved in inflammation, angiogenesis, tumor progression via MDSCs recruitment, ARG1 upregulation and regulation of PD-L1 expression on tumor-infiltrating MDSCs, promotion of CXCL12/CXCR4-mediated recruitment of MDSCs." (PMID 35158779, 2022). "In general, CAFs shape the tumor microenvironment by the production of proinflammatory cytokines, including IL-1β and IL-6, and express the ligands CXCL12, CXCL1, and G-CSF that can drive downstream immunosuppressive signaling pathways." (PMID 36010899, 2022). "In the tumor microenvironment, fibroblasts, which maintain tumor stiffness, can secrete factors such as CXCL12 to inhibit the movement of T cells toward the tumor." (PMID 35402878, 2022). "Tumor cells in advanced cervical cancer, malignant pleural mesothelioma, ovarian cancer and renal cell carcinoma secrete CXCL12, which recruits both TAMs and T-regulatory cells (Tregs) via binding to CXCR4 expressed at high levels on their surface." (PMID 35565443, 2022). "Analysis of this independent data set showed that CXCL12 was downregulated in most other tumor entities but highly upregulated in cultured prostate TEC." (PMID 35717322, 2022). "CXCL12 decreases the expression of the tumor-suppressor ARHGAP10 through VEGF signaling and promotes EOC cell invasion." (PMID 35269786, 2022). "In this process, the overexpression of CXCL12 in tumor cells leads to their gaining the cancer stem cell-like (CSC-like) phenotype, which increases BC cell motility and starts their migration, eventually leading to invasion and metastasis." (PMID 35203510, 2022). "The CXCL12/CXCR4 axis plays a pivotal role in tumor development, survival, angiogenesis, metastasis, and the tumor microenvironment." (PMID 35628268, 2022).